ZNRD2 (zinc ribbon domain containing 2)
Description:
Might play a role in mitosis. Antigenic molecule. Could be a centromere-associated protein. May induce anti-centromere antibodies.
Synonyms: SSSCA1; p27
Tractability: PROTAC: ubiquitination databases record sites on it.
Gene: Protein-coding gene on chromosome 11 (65,570,459 to 65,573,942, forward strand). Ensembl gene ENSG00000173465.
Subcellular location: Cytoplasm
Subcellular location (Human Protein Atlas): Cytosol
Gene Ontology:
Molecular function: protein binding; identical protein binding
Biological process: mitotic cell cycle
Cellular component: cytoplasm
Genetic constraint (gnomAD): Loss-of-function variants: 16 observed, 23.65 expected, observed/expected ratio (o/e) 0.68, 90% interval 0.46 to 1.03. The upper end of that interval is the gene's LOEUF score, 1.03, which puts it in group 4 of 6, group 1 being the genes least tolerant of losing a copy. Missense variants: 269 observed, 271.83 expected, observed/expected ratio (o/e) 0.99, 90% interval 0.89 to 1.1. Synonymous variants: 105 observed, 118.23 expected, observed/expected ratio (o/e) 0.89, 90% interval 0.76 to 1.04.
Homologues: Orthologues: chimpanzee ZNRD2 (100% identical), macaque ZNRD2 (99% identical), dog ZNRD2 (95% identical), pig ZNRD2 (94% identical), guinea pig ZNRD2 (92% identical), mouse Znrd2 (89% identical), rat Znrd2 (89% identical), zebrafish znrd2 (62% identical), tropical clawed frog znrd2 (51% identical), Caenorhabditis elegans Y39A1A.3 (25% identical).
Diseases named in the same sentence as ZNRD2 in open-access papers:
ZNRD2 is named in the same sentence as 8 diseases in open-access papers, as found by Europe PMC text mining. Sharing a sentence is not in itself a finding about the gene and the disease. The quoted sentences say what the papers report.
otosclerosis (1 paper, 2023). Formation of spongy bone in the labyrinth capsule which can progress toward the stapes (stapedial fixation) or anteriorly toward the cochlea leading to conductive, sensorineural, or mixed hearing loss. "Otosclerosis colocalized genetically with the expression of BANF1, MARK3 and SUPT3H in the highest number of tissues (14, 8 and 6, respectively), while the highest causal posterior probability was observed for TELO2 (9.5%), ZNRD2 (6.3%), EHBP1L1 (6.0%)." (PMID 36653343, 2023).
neurodevelopmental disorder (1 paper, 2023). A behavioral and cognitive disorder with onset during the developmental period that involves impaired or aberrant development of intellectual, motor, or social functions. "The E3994A mutant, found in a patient with neurodevelopmental disorders, was located in RLD3 close to the site of ZNRD2 interaction." (PMID 37480851, 2023).
ZNRD2 also shares sentences with these, for which no sentence is quoted: cancer (3 papers); cervical cancer (1); colorectal cancer (1); prostate carcinoma (1); scleroderma (1); Sjögren’s syndrome (1).